LEO1 (LEO1 component of Paf1/RNA polymerase II complex)
Description:
Component of the PAF1 complex (PAF1C) which has multiple functions during transcription by RNA polymerase II and is implicated in regulation of development and maintenance of embryonic stem cell pluripotency. PAF1C associates with RNA polymerase II through interaction with POLR2A CTD non-phosphorylated and 'Ser-2'- and 'Ser-5'-phosphorylated forms and is involved in transcriptional elongation, acting both independently and synergistically with TCEA1 and in cooperation with the DSIF complex and HTATSF1. PAF1C is required for transcription of Hox and Wnt target genes. PAF1C is involved in hematopoiesis and stimulates transcriptional activity of KMT2A/MLL1; it promotes leukemogenesis through association with KMT2A/MLL1-rearranged oncoproteins, such as KMT2A/MLL1-MLLT3/AF9 and KMT2A/MLL1-MLLT1/ENL. PAF1C is involved in histone modifications such as ubiquitination of histone H2B and methylation on histone H3 'Lys-4' (H3K4me3). PAF1C recruits the RNF20/40 E3 ubiquitin-protein ligase complex and the E2 enzyme UBE2A or UBE2B to chromatin which mediate monoubiquitination of 'Lys-120' of histone H2B (H2BK120ub1); UB2A/B-mediated H2B ubiquitination is proposed to be coupled to transcription. PAF1C is involved in mRNA 3' end formation probably through association with cleavage and poly(A) factors. In case of infection by influenza A strain H3N2, PAF1C associates with viral NS1 protein, thereby regulating gene transcription. Involved in polyadenylation of mRNA precursors. Connects PAF1C to Wnt signaling.
Synonyms: RDL
Tractability: PROTAC: ubiquitination databases record sites on it; its protein half-life has been measured.
Gene: Protein-coding gene on chromosome 15 (51,938,025 to 51,971,791, reverse strand). Ensembl gene ENSG00000166477.
Subcellular location: Nucleus
Subcellular location (Human Protein Atlas): Nucleoli fibrillar center; Nucleoplasm; Centrosome
Pathways (Reactome):
Gene expression (Transcription): Formation of RNA Pol II elongation complex; RNA Polymerase II Pre-transcription Events; RNA Polymerase II Transcription Elongation
Chromatin organization: CHD1 and CHD2 subfamily
Disease: Dengue virus activates/modulates innate and adaptive immune responses
Metabolism of proteins: E3 ubiquitin ligases ubiquitinate target proteins
Signal Transduction: Formation of the beta-catenin:TCF transactivating complex
Gene Ontology:
Molecular function: protein binding; RNA polymerase II C-terminal domain phosphoserine binding
Biological process: mRNA 3'-end processing; negative regulation of myeloid cell differentiation; positive regulation of transcription by RNA polymerase II; stem cell population maintenance; transcription elongation by RNA polymerase II; endodermal cell fate commitment; positive regulation of transcription elongation by RNA polymerase II
Cellular component: Cdc73/Paf1 complex; fibrillar center; nucleoplasm; nucleus
Genetic constraint (gnomAD): Loss-of-function variants: 16 observed, 49.83 expected, observed/expected ratio (o/e) 0.32, 90% interval 0.22 to 0.49. The upper end of that interval is the gene's LOEUF score, 0.49, which puts it in group 2 of 6, group 1 being the genes least tolerant of losing a copy. Missense variants: 473 observed, 598.48 expected, observed/expected ratio (o/e) 0.79, 90% interval 0.73 to 0.85. Synonymous variants: 191 observed, 212.19 expected, observed/expected ratio (o/e) 0.9, 90% interval 0.8 to 1.01.
Homologues: Orthologues: chimpanzee LEO1 (100% identical), macaque LEO1 (99% identical), dog LEO1 (98% identical), pig LEO1 (97% identical), mouse Leo1 (94% identical), rat Leo1 (91% identical), rabbit LEO1 (90% identical), guinea pig LEO1 (88% identical), tropical clawed frog leo1 (76% identical), zebrafish leo1 (67% identical), Drosophila melanogaster Atu (39% identical), Caenorhabditis elegans leo-1 (26% identical).
Diseases named in the same sentence as LEO1 in open-access papers:
LEO1 is named in the same sentence as 11 diseases in open-access papers, as found by Europe PMC text mining. Sharing a sentence is not in itself a finding about the gene and the disease. The quoted sentences say what the papers report.
autism spectrum disorder (1 paper, 2026). A spectrum of developmental disorders that includes autism, and Asperger syndrome. "Nevertheless, we recommend that LEO1 be recognized as a disease gene with strong evidence of causation and be included in multigene panels for developmental delay and autism spectrum disorder." (PMID 40993282, 2026).
breast carcinoma (1 paper, 2022). "Interestingly, our results also showed that UBR5 can not only down-regulate the expression of the CDC73 in breast cancer cells, but also additional PAF1C subunits PAF1, CTR9, and LEO1." (PMID 35551175, 2022).
cardiac arrhythmia (1 paper, 2019). Any disturbances of the normal rhythmic beating of the heart or MYOCARDIAL CONTRACTION. "Importantly, we experimentally validate that an approved cardiac arrhythmia and heart failure drug, ouabain, shows potential antitumor activities in lung adenocarcinoma by uniquely targeting a HIF1α/LEO1-mediated cell metabolism pathway." (PMID 31375661, 2019).
colon cancer (1 paper, 2023). "This research was primarily carried out in HCT116 and DLD-1 colon cancer cell lines, and while the basic functions of LEO1 and CDK12 in transcription are likely to be conserved, the effects of LEO1 mutations or CDK12 inhibition on target genes may differ in other cell types." (PMID 37205756, 2023).
neurodevelopmental disorder (1 paper, 2026). A behavioral and cognitive disorder with onset during the developmental period that involves impaired or aberrant development of intellectual, motor, or social functions. "Based on this detailed clinical characterization of a proband and independently ascertained cases with de novo loss-of-function variants, we conclude that LEO1 haploinsufficiency is responsible for a neurodevelopmental disorder." (PMID 40993282, 2026). "Burden analyses in cohorts of neurodevelopmental disorder patients have identified significant enrichment for rare variants in LEO1." (PMID 40993282, 2026). "While burden analyses suggest an association between rare LEO1 variants and an increased risk for neurodevelopmental disorder, the paucity of reported cases has prevented a definitive characterization of the resulting phenotype." (PMID 40993282, 2026). "This analysis supports LEO1 haploinsufficiency as a mechanism for this neurodevelopmental disorder." (PMID 40993282, 2026).
LEO1 also shares sentences with these, for which no sentence is quoted: cancer (2 papers); developmental delays (1); heart failure (1); infection (1); lung adenocarcinoma (1); Obesity (1).